HLA-E (major histocompatibility complex, class I, E)
Diseases named in the same sentence as HLA-E in open-access papers (continued):
Sharing a sentence is not in itself a finding about the gene and the disease.
HCMV infection (32 papers, 2013 to 2025). "In parallel to HLA-EUL40 CD8 T, adaptive memory NKG2C+ NK cells proliferate in response to HCMV infection via the presentation of virally encoded UL40 peptides on HLA-E molecules." (PMID 37187736, 2023). "Recently, we found that HLA-E*01:03 carrier status is associated with cytomegalovirus infection after kidney transplant." (PMID 31394776, 2019). "To examine how the level of total HLA class I and HLA-E in TAP-deficient cells is affected by CMV infection, we established an in vitro infection model using fibroblasts derived from two TAP-deficient patients." (PMID 26500647, 2015). "We further show that increased editing of miR-376a is observed upon HCMV infection and that the edited miR-376a (miR-376a(e)), downregulates the expression of HLA-E to render infected cells susceptible to elimination by NK cells." (PMID 24586166, 2014). "Thus, TAP-deficient fibroblasts retained their HLA-E expression levels (i.e., 30–50% of normal levels) upon CMV infection." (PMID 26500647, 2015). "The finding of NKG2C+ adaptive NK cell populations in patients with TAP deficiency raised the question whether HLA-E expression levels were modulated by HCMV infection in TAP-deficient cells." (PMID 26500647, 2015). "Although NKG2C binds HLA-E with lower affinity than inhibitory receptors, its high dependence on specific viral peptides enables it to play a critical role during HCMV infection and reactivation, shaping highly variable NK cell repertoires among individuals." (PMID 41156609, 2025). "Another aspect that deserves to be further investigated is the capacity to clear EBV+ targets of adaptive NK cells that express the inhibitory CD94/NKG2C receptor for HLA-E and display superior effector functions in the context of HCMV infection." (PMID 39676862, 2024). "Apparently, the presence of hCMV infection, which generates different HLA-E-stabilizing peptides, induces the formation of hCMV-specific NK cells, the response of which is accelerated then by the presentation of the LFL peptide derived from HLA-G." (PMID 38534374, 2024). "It outlines functional characteristics and molecular features of CD94/NKG2C, its interactions with HLA-E molecule and presented antigens, pointing out a key role of this receptor in immunosurveillance, especially in the human cytomegalovirus infection." (PMID 36899273, 2023). "The tetramers that we used include HLA-A2pp65 tetramers and HLA-EUL40 tetramers to decipher HLA-E-restricted CD8 T cells induced in the response to HCMV infection." (PMID 35008688, 2021). "It has been shown that HLA-E-restricted T cells accumulate upon HCMV infection, possess the CD45RA+CD28−CD27−CCR7−CD56+ phenotype and are able to recognize peptides derived from HCMV protein UL40 in the context of HLA-E." (PMID 33664730, 2020). "The use of 8 different HLA-E/UL40 peptide tetramers allowed us to decipher the spectrum of HLA-EUL40 responses generated post HCMV infection." (PMID 29709038, 2018). "Macrophages and monocytes express HLA-E and de novo induction of monocyte HLA-G cell surface expression was reported for active HCMV infection and reactivation of latent infection in vitro." (PMID 30386347, 2018). "During HCMV infection, edited miR-376 down-regulates the expression of HLA-E which promotes NK cell ability to eliminate the HCMV infected cells." (PMID 25856272, 2015). "We next wanted to demonstrate that miR-376a(e) specifically controls the endogenous expression of HLA-E during HCMV infection." (PMID 24586166, 2014). "Together, these results demonstrate the dominance of the inhibitory signal generated by NKG2A in controlling NK cell activity and the importance of the regulation of HLA-E by miR-376a(e) during HCMV infection." (PMID 24586166, 2014). "After we demonstrated that antagonizing ADAR1-p110 and miR-376a(e) affects HLA-E during HCMV infection we next wanted to test the functional implications of these findings." (PMID 24586166, 2014).
HCMV infection (continued). "We initially validated that the miR-376a(e) binding sites in the 3′ UTR of HLA-E are targeted during HCMV infection." (PMID 24586166, 2014). "The organ cultures were next immunofluorescencenly stained for ADAR1 or HLA-E expression either early (36 hrs) or late (7days) during HCMV infection." (PMID 24586166, 2014). "In contrast, during HCMV infection only the anti-miR-376a(e) sponge led to increase levels of HLA-E." (PMID 24586166, 2014). "This striking observation of HLA-E downregulation by HCMV prompted us to perform further analyses comparing the impact of HCMV infection in additional decidual fibroblasts and in other cells." (PMID 23592985, 2013). "In addition, we investigated HLA‐E due to its role in the expansion of NKG2C+ adaptive NK cells upon HCMV infection." (PMID 39931744, 2025). "Consistent with our previous findings, the present study investigating kidney transplanted patients with a primary HCMV infection post-transplantation shows that HLA-E-restricted CD8T cells, a subset of anti-HCMV CD8T cells, are frequently induced post-infection." (PMID 36532017, 2022). "In some HCMV infections, HLA-E-restricted T cells may even play a major role in anti-virus defenses, given the over-expression of HLA-E molecules and down-regulation of HLA-I molecules." (PMID 34446788, 2021). "However, HLA-E can also be recognized by the paired NK activating receptor CD94/NKG2C and by HLA-E-specific T cells; expansions of CD94/NKG2C+ NK cells are commonly associated with HCMV infection." (PMID 32510303, 2020). "Together with recent studies, that show the profound impact of the HLA-G-derived leader peptide, we are tempted to speculate that only CMV infection provides both, elevated HLA-E and HLA-G expression on a single cell level." (PMID 30386347, 2018). "Furthermore HLA-E molecules play an important part in viral interference, for example, human cytomegalovirus (HCMV) infections." (PMID 26366178, 2015). "We next proceeded to investigate whether ADAR1 has a role in the regulation of HLA-E during HCMV infection." (PMID 24586166, 2014). "Because we demonstrated that ADAR1-p110 and editing of miR-376a are induced specifically following HCMV infection and since we showed that miR-376a(e) regulates HLA-E, we next tested whether miR-376a(e) controls HLA-E during HCMV infection." (PMID 24586166, 2014). "Finally we demonstrate that in decidual tissues ADAR1-p110 is induced and that HLA-E levels are reduced in response to HCMV infection." (PMID 24586166, 2014). "We then investigated whether HCMV infection affected the expression level of HLA-E cell surface molecules." (PMID 23592985, 2013). "The role of HLA-E-restricted CD8 T cells in the outcome on HCMV infection is still unknown." (PMID 35008688, 2021). "The role of HLA-E in controlling NK cell activity in the context of viral interference could be shown recently by demonstrating how miR-376a(e) regulates HLA-E expression during HCMV infection." (PMID 25401109, 2014). "In particular, during HCMV infection, adaptive NKG2C+ NK cells can accurately discriminate UL40-derived peptides presented by HLA-E, with even a single amino acid difference affecting their recognition and activation." (PMID 41156609, 2025). "When engaged by the HLA-E/UL40-derived peptide complex, NKG2C stimulates NK cell cytotoxicity and cytokine production, contributing to the control of HCMV infection." (PMID 41283666, 2025). "In HCMV infections, NKG2C+ NK cell expansion is dependent on the presentation of a virus-derived UL40 peptide by HLA-E." (PMID 34871302, 2021). "Selective recognition of peptides from HCMV by NKG2C in the context of HLA-E driven NK cell proliferation implies a direct role for NKG2C in NK cell adaptation and functional differentiation to HCMV infection." (PMID 30857329, 2019).
HCMV infection (continued). "Therefore, CD8low, CD45RAhigh CD56+, CD57high,CD158+, PD-1- immune profile defines a set of HLA-E-restricted αβCD8T, γδT (mostly δ2-γδT) and CD57+ NK cells induced by HCMV infection." (PMID 36532017, 2022). "Our study investigated the presence of circulating HLA-E-restricted CD8 T cells in a cohort of kidney transplant recipients (KTR, n = 121) during either an active HCMV infection (at primary infection or at reactivation) or at latency and in HCMV seropositive (HCMV+) healthy volunteers (HV, n = 25)." (PMID 29709038, 2018). "We found that HCMV infection lead to a further decrease in overall levels of HLA class I without influencing HLA-E that was maintained at approximately 30–50% of that in normal individuals." (PMID 26500647, 2015). "Upon CMV infection, TAP-deficient fibroblasts manifested a further reduction of total HLA class I expression, whereas HLA-E expression remained intact compared to non-infected fibroblasts." (PMID 26500647, 2015). "Thus we concluded that following HCMV infection ADAR-p110 is induced, miR-376a is edited and that the edited miRNA, miR-376a(e), regulates the expression of HLA-E." (PMID 24586166, 2014). "Both membrane bound and soluble levels of HLA-G are reported to be increased in untreated HIV-1 infection and during HCMV infection and have been shown to correlate with blood IFN-γ concentrations and could therefore represent a source of HLA-E peptides in T/T individuals." (PMID 32132995, 2020). "A similar setting seems possible for endothelial cells that were reported to trigger NKG2C+ NK cells upon primary CMV infection and that represent a major non-lymphoid cell type displaying substantial HLA-E expression, particularly under inflammatory conditions." (PMID 30386347, 2018). "Thus, to demonstrate the induction of ADAR1 and reduction in HLA-E expression following HCMV infection in physiological settings, we used a decidua organ culture model and observed that during HCMV infection ADAR1-p110 expression is induced and that HLA-E expression is reduced." (PMID 24586166, 2014). "Hence HCMV infection provides peptides that may substitute for host HLA-I-derived HLA-E stabilizing non-americ peptides in T/T donors." (PMID 32132995, 2020).
breast carcinoma (28 papers, 2011 to 2025). "The literature suggests that HLA-E expression in tumors is associated with poor outcomes in gastric, pancreatic, and breast cancer patients." (PMID 39845968, 2024). "Other studies found that LAG3 and HLA-E were associated with immunosuppressive effects and tumor immune evasion in breast cancer, gastric cancer, and ovarian cancer, among others." (PMID 37007962, 2023). "A concomitant loss of HLA class Ia and high expression of HLA-G and HLA-E is associated with a worse prognosis and increased metastatic capacity in breast cancer." (PMID 32560316, 2020). "Associations between HLA-E expression and improved survival have been described for colorectal carcinoma, breast carcinoma, and glioblastoma." (PMID 22947189, 2012). "Another example of HLA-E association with poor prognosis is a recent study on early-stage breast carcinoma." (PMID 22032294, 2011). "A poor prognosis has been linked to HLA-E expression in various malignancies including colorectal cancer, gastric cancer, gynecological cancers, non-small cell lung cancer (NSCLC) and breast cancer." (PMID 40066089, 2025). "The present study compares the antitumor activity of KLRC1KO and wild-type (WT) NK cells against several HLA-E+ solid tumor cell lines in vitro and in an HLA-E+ breast cancer xenograft mouse model." (PMID 37675109, 2023). "It would be relevant to further evaluate the additive effect of this approach on primary breast cancer with high levels of HLA-E." (PMID 34203549, 2021). "HLA-E and HLA-F were also investigated in breast cancer and other solid tumors where it was observed that HLA-F expression positively correlated with tumor size and poor five-year survival rate." (PMID 32784928, 2020). "For instance, expression of HLA-E has been reported to resulted in a worse relapse-free period for patients with breast cancer." (PMID 32066399, 2020). "In a study of 677 patients with early breast cancer, it has been shown that patients with lost classical HLA-I and expressing HLA-E and HLA-G show a shorter relapse free period, compared to those expressing classical HLA-I." (PMID 32784928, 2020). "Aberrant expression of HLA-E has been identified in various human malignancies, such as breast cancer, gastric cancer, rectal cancer, and colorectal cancer." (PMID 32066399, 2020). "A deep study of the role of high glucose in HLA-E expression in co-cultures of breast cancer cells and PBMCs should be also investigated." (PMID 33096896, 2020). "For example, similarly to the publicly available breast cancer dataset, we observed a decrease in HLA-E expression in the proprietary ER + /HER2- breast tumors compared to the normal adjacent to tumor tissue, and an increased infiltration of NK cells in four out of five patients." (PMID 38281021, 2024). "In breast cancer patients, HLA-E expression was detected in 20–50% of samples." (PMID 34203549, 2021). "Similarly, clinical studies have shown that patients with colorectal cancer, breast cancer, or glioblastoma and high HLA-E expression in the tumor tissue have poorer prognoses." (PMID 27322426, 2016). "Therefore, it seems likely that high HLA-E expression will also limit NK cell anti-breast-cancer responses, and in those cases, blocking antibodies such as the anti-NKG2A antibody monalizumab might need to be considered." (PMID 34203549, 2021). "Furthermore, HLA-E and -F expression has been found in metastases from breast cancer." (PMID 31013867, 2019). "CLEC2B, HLA-E, IL15, and VIM all appear in the 4 subtypes at the same time, which may mean that they play a more general role in different subtypes of breast cancer." (PMID 33304391, 2020). "HLA-E and HLA-G overexpression has been shown in HER2+ type of breast cancer." (PMID 32784928, 2020). "We did not have breast cancer cells available that expressed HLA-E." (PMID 34203549, 2021). "Both breast cancer cell lines used in this study did not express HLA-E." (PMID 34203549, 2021).
breast carcinoma (continued). "We compared the anti-tumor response of NKG2A+ vs. NKG2A− NK cell subsets in the CD107a assays to test whether licensing by NKG2A can have a positive effect on NK cell degranulation against HLA-E negative breast cancer targets." (PMID 34203549, 2021). "Interestingly, previous studies have revealed that selinexor pre-treatment increase T cell activation against B cell malignancies and breast cancer cells however the contribution of HLA-E/NKG2A interactions in these settings were not investigated." (PMID 34926302, 2021). "This suggests that there could be an interaction between these two classes of HLA molecules and that the presence of HLA-E/HLA-G with or without HLA-I can predict the outcome of relapse free period of breast cancer patients." (PMID 32784928, 2020). "A few studies in breast cancer and cervical adenocarcinoma have reported survival benefit for HLA-E expressing tumors while others, similar to us, reported a negative effect of HLA-E on OS in ovarian cancer, colorectal cancer and gastric cancer." (PMID 26658106, 2016).
colorectal cancer (24 papers, 2011 to 2025). A primary or metastatic malignant neoplasm that affects the colon or rectum. "At the time of proof-editing a paper appeared in PubMed describing a poor prognosis associated with HLA-E expression in colorectal carcinoma and NKG2A expression in the lymphoid infiltrate." (PMID 22032294, 2011). "Differential expression of exons 1 and 2 could specifically enhance HLA-E expression to resolve inflammation; over-expression of HLA-E has been previously reported in tumor cells in colorectal cancer and was associated with the inhibition of NK or CD94+/NKG2A+/CD8+ T cells infiltrating tumor tissue." (PMID 28303134, 2017). "An ongoing clinical trial using anti-NKG2A monoclonal antibodies in colorectal cancer demonstrates that blocking HLA-E overexpression shows promising results (NCT02980146) (HLA-E CCR)." (PMID 36829496, 2023). "Similar to the overexpression of HLA-E in unstable microsatellite tumors in colorectal cancer, HLA-E was preferentially overexpressed in HRD HGSC, although the germline or somatic BRCA mutation status was not explored in this study." (PMID 38067396, 2023). "Studies in colorectal cancer have shown that HLA-E is correlated with tumor metastasis and has a predictive value for OS." (PMID 35127943, 2022). "In line with HLA-E overexpression described in microsatellite instable tumors in colorectal cancer, we also reported a higher prevalence of HLA-E overexpression in HRD tumors that are known to be more immune infiltrated, due to their genomic instability." (PMID 35267497, 2022). "HLA-G is a known ligand for CD8αα, which is expressed on some colorectal cancer, while HLA-E is mainly expressed in human endothelial cells and is highly expressed in tumor cells." (PMID 34759930, 2021). "The overexpression of HLA-E on tumor cells has recently been reported in colorectal cancer and was pointed out as a biomarker for tumor cell differentiation." (PMID 25401109, 2014). "Studies on colorectal cancer cell lines showed accordingly an overexpression of HLA-E that was correlated with the malignancy stage and furthermore the release of soluble HLA-E molecules from these cell lines." (PMID 25401109, 2014). "Although intracellular transport of HLA-E is believed to be quite inefficient, colorectal carcinoma cells (like most neoplastic cell lines) co-express on the surface HLA-E and classical HLA class I molecules, including HLA-A." (PMID 22032294, 2011). "The present immunohistochemical study of colorectal carcinoma lesions with the MEM-E/02 antibody reveals that high expression of HLA-E significantly correlates with high expression of HLA-A, but not HLA-B or HLA-C." (PMID 22032294, 2011). "We conclude that HLA-E and at least its preferred ligand donors (from the HLA-A locus) are coordinately expressed in colorectal carcinoma lesions in vivo." (PMID 22032294, 2011). "Moreover, expression levels of HLA-G or HLA-E and the combined expression of both molecules were all negatively correlated with OS of colorectal cancer patients." (PMID 27652273, 2016). "HLA-E alleles did not affect the clinical outcome of patients with stage III colorectal cancer." (PMID 31690066, 2019). "Finally, flow cytometry of 3 representative colorectal carcinoma cell lines provided evidence that at least some of the denatured HLA-A and HLA-E molecules detected by HCA2 and MEM-E/02 on archival tissues derive from native molecules that are co-expressed on the surface of live cells." (PMID 22032294, 2011). "Colorectal carcinomas from stage II/III patients (n = 149), each paired with morphologically normal colonic mucosa from the same patient, were stained by immunohistochemistry with the HLA-E-specific MEM-E/02 antibody." (PMID 22032294, 2011). "In addition to regulating HLA-E surface expression, bortezomib has also been shown to activate an anti-cancer NK cell response via upregulation of FAS and death receptor 5 (DR5) on leukaemia and colorectal cancer cell lines." (PMID 36560403, 2022).